MYB (MYB proto-oncogene, transcription factor)
Diseases named in the same sentence as MYB in open-access papers (continued):
Sharing a sentence is not in itself a finding about the gene and the disease.
myeloid leukemia (18 papers, 2015 to 2024). A clonal proliferation of myeloid cells and their precursors in the bone marrow, peripheral blood, and spleen. "This study provided proof-of-principle that targeting of MYB transcriptional activity with a chemical compound is feasible and showed that the inhibition of the MYB-p300 interaction induces differentiation and apoptosis in human myeloid leukemia cell lines." (PMID 38542205, 2024). "Knockdown of MYB in myeloid leukemia cells induced pro-apoptotic Bcl-2 related ovarian killer (BOK) and Bcl-2 interacting mediator of cell death (BIM) and led to sensitization to panobinostat, which is another clinically approved HDAC inhibitor." (PMID 38835346, 2024). "In a previous study, overexpression of MYB-WT in the entire hematopoietic system was sufficient to induce lymphoid or myeloid leukemias in mice." (PMID 39499902, 2024). "Previous studies have shown that HDACi (e.g. givinostat and vorinostat, also identified in our screen) downregulate MYB gene expression in myeloproliferative neoplasms and myeloid leukemias." (PMID 37077825, 2023). "To characterize the MYB-inhibitory potential of the kinase inhibitors in a relevant biologically setting, we studied their effects on the human myeloid leukemia cell line HL60." (PMID 35406726, 2022). "Distal regulatory elements have also been shown to regulate MYB in human myeloid leukemia cell lines." (PMID 35408829, 2022). "Taken together, our data revealed that enhancer elements at −34k are required for MYB expression, TF binding, and epigenetic modification are closely involved in this process in human myeloid leukemia cells." (PMID 33637692, 2021). "Further study showed the dynamic DNA looping formation, TF binding, and epigenetic modifications at the −34k region are involved in MYB expression during differentiation of human myeloid leukemia cells." (PMID 33637692, 2021). "Unexpectedly, this work showed that the topoisomerase II inhibitors teniposide and etoposide also affect MYB activity and its expression in myeloid leukemia cells." (PMID 30177851, 2018). "By contrast, we observed a strong reduction of MYB expression in several myeloid leukemia cell lines that was apparently due to the degradation of the protein." (PMID 30177851, 2018). "Similar observations were made for HL60 and U937 cells, indicating that down-regulation of MYB expression by teniposide is common to several myeloid leukemia cell lines." (PMID 30177851, 2018). "On the other hand, MYB expression is known to be critical for myeloid leukemia induced by SETBP1 activation, and its inhibition could be beneficial for treating SETBP1-associated neoplasms." (PMID 38165902, 2024). "In addition, mice bearing myeloid leukemia cells with inducible MYB shRNA showed prolonged survival when panobinostat was combined with MYB knockdown." (PMID 38835346, 2024). "Other studies have further stated that regulation of VEGF production by MYB has implications for the potential role of MYB in myeloid leukemia and solid tumors, wherein VEGF may act as an autocrine growth factor." (PMID 33407591, 2021). "In addition, dexamethasone was able to suppress MYB in myeloid leukemia cells." (PMID 38835346, 2024). "Teniposide induced a decrease of MYB expression in several myeloid leukemia cell lines, which appears to be mainly due to proteasomal degradation of MYB rather than altered transcription or RNA stability." (PMID 30177851, 2018).
T-cell acute lymphoblastic leukemia (18 papers, 2011 to 2025). Acute lymphoblastic leukemia of T-cell origin. "Gene duplication has previously been shown as a mechanism of MYB activation in T-cell acute lymphoblastic leukemia." (PMID 35954356, 2022). "The link between MYB aberrations and human cancer was recently strengthened by the detection of duplications and translocations of the MYB gene in T cell acute lymphoblastic leukaemia." (PMID 21338522, 2011). "In addition, it has been suggested that miR-193b-3p functions as a tumor suppressor in T-cell acute lymphoblastic leukemia and can directly regulate the MYB oncogene." (PMID 30390708, 2018). "Furthermore, it has been observed that translocation of TCRB(T-cell receptor beta) gene to region telomeric of MYB, results in MYB overexpression in childhood T-cell acute lymphoblastic leukemia." (PMID 27533466, 2016). "In T-cell acute lymphoblastic leukemia (T-ALL), a 2–18 bp fragment is inserted into the noncoding intergenic region of the TAL1 gene to create a de novo binding site for MYB, thereby initiating SE formation and increasing TAL1 expression." (PMID 37501079, 2023).
neuroblastoma (17 papers, 2010 to 2025). Neuroblastoma (NB) is the most common solid, extracranial childhood tumor. "MYB is a transcription factor that cooperates with MYCN in cell cycle regulation of MYCN-amplified neuroblastomas." (PMID 26893368, 2016). "ID2 is a helix-loop-helix transcription factor controlled by MYC proteins that blocks differentiation and promotes cell proliferation, and MYB is a transcription factor that cooperates with MYCN in cell cycle regulation of MYCN-amplified neuroblastomas." (PMID 27242543, 2016). "MYCN together with MYB were shown to be involved in a reciprocal regulatory loop promoting survival/proliferation of neuroblastoma cells." (PMID 23702334, 2013). "In order to illustrate the advantage of HTSplotter on genetic-chemical perturbagen assessed in real-time, we applied our tool to an in-house assessment of exogenous overexpression of the SOX11 gene in the SH-EP neuroblastoma cell line, in combination with the MYB inhibitor celastrol." (PMID 38181013, 2024). "Similarly to MYBL2, MYB expression is significantly increased in MYCN-amplified neuroblastomas predicting poor survival." (PMID 25477524, 2015). "MYB regulates the neuroblastoma oncogene MYCN, by controlling its expression and amplification in neuroblastoma lines." (PMID 33466745, 2021). "Concomitantly, genes that critically support neuroblastoma proliferation were down-regulated, such as MYCN, inhibitor of differentiation 2 (ID2) and MYB." (PMID 27242543, 2016). "The alkaloids camptothecin and topotecan, which reportedly interacted with G-quadruplex regions of the MYB promoter and led to MYB suppression, also suppressed MYBL2 and MYCN expression in IMR-32, Kelly, and LAN-5 neuroblastoma cells accompanied by apoptosis induction." (PMID 38835346, 2024). "In the disease association analysis (neoplasms, cancer or viral infections, breast neoplasms, neuroblastoma), the LMO3, MYB and BIRC3 oncogenes were also significantly upregulated whereas the WISP2, IGFBP5 and RASSF2 tumour suppressor genes were significantly downregulated in FFs compared to NFs." (PMID 28717200, 2017).
ovarian carcinoma (17 papers, 2018 to 2025). A malignant neoplasm originating from the surface ovarian epithelium. "Various studies have shown the association between TOP2A and ovarian cancer; however, in-depth investigations about the mechanism of MYB in ovarian cancer remain scarce." (PMID 33407591, 2021). "Moreover, in ovarian cancer, high MYB expression can cause tumor cells to resist cisplatin." (PMID 34876130, 2021). "In ovarian cancer (OC) cells, MYB overexpression induces cisplatin resistance by activating the NF-κB and STAT3 signaling pathways, whereas MYB silencing or inhibition restores cisplatin sensitivity." (PMID 40725394, 2025). "For example, hsa_circ_0015326 facilitated the progression of ovarian cancer by regulating the miR-127-3p/MYB axis." (PMID 35281849, 2022). "The sh-MYB treatment led to significantly reduced expressions of MYB in ovarian cancer cells, while miR-424 inhibitor transfection brought about the opposite results." (PMID 33407591, 2021). "Subsequently, the characterized MSCs and isolated EVs were co-cultured with ovarian cancer cells, followed by determination of the expression patterns of miR-424, MYB, vascular endothelial growth factor (VEGF), and VEGF receptor (VEGFR), respectively." (PMID 33407591, 2021). "Collectively, our findings indicate that MSC-derived EVs transfer miR-424 to down-regulate MYB, which ultimately led to the inhibition of the tumorigenesis and angiogenesis of ovarian cancer." (PMID 33407591, 2021). "LOC102724169 suppresses the expression of MYB in ovarian cancer with chronic stress (OCCS) by weakening PI3K/Akt signal transduction, which enhances the chemosensitivity to cisplatin and plays an antitumor role in OCCS." (PMID 34876130, 2021). "Our data exhibited that MYB was highly-expressed and miR-424 was poorly-expressed in ovarian cancer." (PMID 33407591, 2021). "In comparison with the adjacent ovarian epithelium tissues, ovarian cancer tissues presented with higher positive expression of MYB (p < 0.05)." (PMID 33407591, 2021). "Results from the PPI network revealed that the KIT, TOP2A, and MYB genes exhibited a higher correlation with other genes, and were thus likely to affect the development of ovarian cancer." (PMID 33407591, 2021). "Immunohistochemistry was employed to detect the positive expressions of MYB in ovarian cancer, and it was found that the positive expression of MYB was brown-yellow in color and located in the nucleus." (PMID 33407591, 2021). "The data mining revealed significantly higher expression of MYB transcript (false discovery rate-adjusted) in a large ovarian cancer cohort (n = 426) compared to the normal ovarian tissues (n = 88)." (PMID 34145334, 2021). "Our initial findings revealed that MYB was highly-expressed and miR-424 was poorly-expressed in ovarian cancer." (PMID 33407591, 2021). "Our study examined MYB expression in a larger cohort of normal and ovarian cancer cases and found its widespread overexpression in all EOC histological subtypes." (PMID 34145334, 2021). "More importantly, experiments have shown that MSCs can transport miR-424 to ovarian cancer cells to target MYB to further inhibit the expression of VEGF and the proliferation, migration and tube formation of endothelial cells, to block angiogenesis." (PMID 34876130, 2021). "Overall, these results demonstrated that miR-424 suppressed the proliferation, migration, and invasion of ovarian cancer cells by inhibiting MYB, and miR-424 reduced the expressions of VEGF and VEGFR." (PMID 33407591, 2021). "In the present study, we investigated MYB expression in situ by immunohistochemistry in normal and malignant ovarian tumors." (PMID 34145334, 2021). "The consistent results in two different ovarian cancer cell lines provided us the confidence that c-MYB plays a role in determining cisplatin resistance, thus confirming the previously published work of other researchers." (PMID 32327705, 2020).
ovarian carcinoma (continued). "The objective of this study was to further evaluate role of c-MYB in ovarian cancer’s cisplatin resistance." (PMID 32327705, 2020). "It has been reported previously that c-MYB greatly influences cisplatin resistance in ovarian cancer cells." (PMID 32327705, 2020). "One of the key findings of this work was that c-MYB expression is relatively higher in ovarian cancer patients, as compared to normal controls, thus clearly suggesting a role of c-MYB in ovarian cancer pathogenesis." (PMID 32327705, 2020). "In summary, based on the presented evidences, we have provided mechanistic details of cisplatin resistance in ovarian cancer by performing functional studies employing overexpression and silencing of c-MYB and miR-21." (PMID 32327705, 2020). "We, therefore, focused on the role of MYB on ovarian cancer." (PMID 33407591, 2021). "Similarly, a previous study attributed up-regulated c-MYB levels to the damaging effect on the survival of patient with ovarian cancer." (PMID 33407591, 2021). "Additionally, we illustrated that MSCs secreted miR-424-containing EVs, which suppressed the proliferation, migration, and tube formation of HUVECs via MYB inhibition and ultimately, attenuated the tumorigenesis and angiogenesis of ovarian cancer." (PMID 33407591, 2021). "Moreover, hsa_circ_0015326 sponges miR-127-3p to regulate MYB signaling, which is closely related to the occurrence and development of ovarian cancer." (PMID 34876130, 2021). "Moreover, the heat map for the expression patterns of the first 150 DEGs in GSE4122 was plotted, which revealed that TOP2A and MYB were highly-expressed in ovarian cancer." (PMID 33407591, 2021). "Based upon our observation that c-MYB overexpression induces miR-21 and the cisplatin resistance of ovarian cancer cells, and that such condition leads to activation of wnt signaling, we further tested if silencing of c-MYB could have the reverse effects." (PMID 32327705, 2020). "c-MYB has been reported to be elevated in few cancers, including in ovarian cancer." (PMID 32327705, 2020). "In our study, we found that MSCs could deliver miR-424 into ovarian cancer cells to target MYB, which further inhibited the expression of VEGF and also endothelial cell proliferation, migration as well as tube formation, thereby suppressing the angiogenesis of ovarian cancer." (PMID 33407591, 2021). "Therefore, we speculated that miR-424 affected ovarian cancer by targeting MYB." (PMID 33407591, 2021). "Moreover, high expression of c-MYB has also been deciphered to be positively-correlated with tumor differentiation, ascites, lymph node metastasis and FIGO in patients affected by epithelial ovarian cancer." (PMID 33407591, 2021). "Moreover, the expression of c-MYB correlated with higher grade ovarian cancer which suggested a direct relationship between c-MYB expression and aggressive ovarian cancer." (PMID 32327705, 2020). "For example, SOX9, MYB, and ESRP1 promote ovarian cancer cell proliferation." (PMID 32076467, 2020). "The new regulatory model of “lncRNA-MYB” provides new perspectives for LOC102724169 as a chronic stress-related molecule and also provides mechanistic insight into exploring the cancer-promoting mechanism of MYB in OCCS, which may be a promising therapeutic strategy for ovarian cancer." (PMID 33850634, 2021). "However, in spite of such activity of miR-21, its possible role in c-MYB induced cisplatin resistance of ovarian cancer has never been reported." (PMID 32327705, 2020).
sickle cell disease (17 papers, 2009 to 2026). Sickle cell anemias are chronic hemolytic diseases that may induce three types of acute accidents: severe anemia, severe bacterial infections, and ischemic vasoocclusive accidents (VOA) caused by sickle-shaped red blood cells obstructing small blood vessels and capillaries. "Rare missense mutations of MYB were associated with increased HbF in African Americans with sickle cell anemia." (PMID 26215470, 2015). "Two studies, one in a normal population and the other in sickle cell anemia, showed that BCL11A, the HBS1l-MYB interval and variants in HBB were associated with HbA2 level." (PMID 26215470, 2015).
prostate carcinoma (16 papers, 2012 to 2025). A carcinoma that arises from epithelial cells of the prostate gland. "Abiraterone-sensitive prostate cancer cells revealed much higher MYB levels than abiraterone-resistant cells, and the reduction of MYB signaling seemed responsible for the development of abiraterone resistance." (PMID 38835346, 2024). "First, we used the DepMap database through the Broad Institute to determine the dependency of the MYB genes in human prostate cancer cell lines." (PMID 39113611, 2024). "The treatment of androgen-dependent prostate cancer cells with the antiandrogen enzalutamide also increased MYB expression, while a synthetic androgen (R1881) suppressed MYB." (PMID 38835346, 2024). "In addition, racially disparate expression of MYB in Black and White prostate cancer warrants future studies to characterize mechanisms underlying its dysregulation in these racial subgroups and investigate if MYB targeting could be helpful in closing the disparity gaps." (PMID 38089573, 2023). "MYB acts as a potentiator of aggressiveness and castration resistance in prostate cancer (PCa) through aberrant activation of androgen receptor (AR) signaling." (PMID 38089573, 2023). "MYB, a proto-oncogene, is overexpressed in prostate cancer (PCa) and promotes its growth, aggressiveness, and resistance to androgen-deprivation therapy." (PMID 36410437, 2022). "MYB-overexpressing prostate cancer cells retain AR in the nucleus, even in androgen-deprived conditions, leading to enhanced transcriptional activity." (PMID 36551557, 2022). "It is known that MYB overexpression plays an important role in androgen-depletion resistance and prostate cancer aggressiveness." (PMID 36551557, 2022). "In addition, the circ_0004087/SND1/MYB/BUB1 axis was reported to modulate the error mitosis correction mechanism in prostate cancer cells." (PMID 36803376, 2023). "Accordingly, TSPX-dependent suppression of MYB expression could constitute part of its tumor suppressor functions in castration resistant prostate cancer." (PMID 30863497, 2019). "We showed that ectopic expression of MYB directly transactivates the BUB1 gene by binding to its promoter region, in line with what was recently observed by Cheng and colleagues in prostate cancer." (PMID 38112379, 2024). "Transcriptome analyses demonstrated that the expression levels of various cancer-drivers/oncogenes, including MYC and MYB, were negatively correlated with that of TSPX in both LNCaP cells and clinical prostate cancer samples." (PMID 30863497, 2019). "Among these six, HLF, JUN, c-MYC, EGR1, SMAD1, and HIF1A, were also identified as PTEN-controlled TFs, and four, ESR2, MYB, RELA, and USF1, as prostate cancer-related TFs." (PMID 22347425, 2012). "On the other hand, the expression levels of MYC and MYB in TSPX-low prostate cancer samples were significantly higher than those in both non-tumor prostate samples and TSPX-high prostate cancer samples." (PMID 30863497, 2019). "For example, the expression levels of cancer-drivers/oncogenes MYC, MYB, and AR, whose roles in prostate cancer have been well established, were consistently lower in both TSPX-overexpressing LNCaP cells and TSPX-high clinical prostate cancer samples than the corresponding controls." (PMID 30863497, 2019). "MYB silencing and the CHK1 inhibitor AZD7762 showed synergistic effects with olaparib in androgen receptor (AR)-positive and -negative prostate cancer cells." (PMID 38835346, 2024).